TGFB1 (transforming growth factor beta 1)
Diseases named in the same sentence as TGFB1 in open-access papers (continued):
Sharing a sentence is not in itself a finding about the gene and the disease.
breast cancer (continued). "Recently, miR-506 has been shown to regulate TGFβ1-induced EMT of breast cancer cells through targeting EMT-related gene expression." (PMID 30386180, 2018). "We are the first to show that two different mechanisms of MET regulation are merged by TGFβ1 in aggressive breast cancer cell lines and tumor tissue." (PMID 30004628, 2018). "We recently reported that BMP7 also antagonizes the effects of TGFβ1 in breast cancer (BC) tumorigenesis-related EMT." (PMID 28407692, 2017). "Previous studies suggested that HIF-1α- or TGFβ1-induced miR-382-5p expression led to the inhibition of the ERβ-RERG tumor suppressive signaling cascade in breast cancer." (PMID 27705918, 2017). "Inhibitors of TGFB1 are in currently in phase III clinical trials in other malignancies, thus identifying the connection between leptin and TGFB1 will open new therapeutic opportunities for improving outcomes for obese breast cancer patients." (PMID 28542577, 2017). "We observed a 27.5% increase in TGFβ1 levels compared to MEF-alone when MDA breast cancer cells were co-cultured with MEFs." (PMID 28515430, 2017). "A better understanding of the pathways involved in poor cancer outcomes due to obesity will allow us to use rational combinations of agents such as TGFB1 antagonists, anti-estrogens, and metformin for improving outcomes in obese breast cancer patients." (PMID 28542577, 2017). "For example, TGFB1 and VEGFA are inferred to be the top two key genes mediating obesity-breast cancer connection in modules associated with brain development." (PMID 29156709, 2017). "In agreement with previous reports in MCF-10A breast cancer cells, TGFB1 knockdown also decreased miR-503 expression." (PMID 28445989, 2017). "Smad2 and Smad3 play differential roles in executing TGFβ1 signaling resulting in either suppression or promotion of breast cancer progression." (PMID 27641158, 2016). "We also observed that MDA-9 and TGFβ1 were co-expressed in breast cancer patient samples in the TCGA database using Oncomine." (PMID 27863394, 2016). "Results of a study evaluating the role of TIF-1γ and its interaction with TGFβ1/SMAD4 signaling pathway as a prognostic factor in operable breast cancer have been published recently." (PMID 27561848, 2016). "WISP4 knockdown by sh-CCN5 in MCF-7 breast cancer cells leads to an increased expression of the components of the TGFB1 (TGF-β) signaling pathway and induction of breast cancer invasiveness." (PMID 26395334, 2015). "There is a crosstalk between the TIF1γ and the TGFβ1/SMAD4 signaling that deteriorates the outcome of operable breast cancer patients and when combined together they can serve as an effective prognostic tool for those patients." (PMID 26040677, 2015). "Our results demonstrate an important role of lysosomal proteolysis in cellular remodeling during EMT and a pivotal contribution of lysosomal cysteine cathepsins to TGFβ-1 induced acquisition of breast cancer cell invasiveness." (PMID 25744631, 2015). "To begin to address this, we performed gene expression profiling of mammary tumor EpRas cells that had been allowed to adopt an EMT program after long-term treatment with transforming growth factor beta 1 (TGF-β1) for 2 weeks." (PMID 25674539, 2015). "Our present work clearly concludes that there is a crosstalk between the TIF1γ and the TGFβ1/SMAD4 pathway that can predict poorer outcome in operable breast cancer patients." (PMID 26040677, 2015). "Strikingly, the ability of TGFβ1 expression to predict the poor outcome in breast cancer patients was restricted to TIF1γ expressing tumors." (PMID 26040677, 2015). "The CHEK2, TGFβ1, CASP8 and ATM genes belong to the ‘low to moderate-risk’ breast cancer susceptibility genes." (PMID 26124080, 2015). "Using Neu-induced mammary tumor models with increased activity of TGFβ signaling (MMTV/ALK5 and MMTV/TGFβ1), it was possible to induce that active TGFβ signaling accelerates metastasis and the number of circulating tumor cells." (PMID 25280532, 2014).
breast cancer (continued). "In this work the L10P SNP of TGFβ1 was genotyped in 274 breast cancer patients and 252 female controls." (PMID 24891760, 2014). "The third model involved the well-differentiated, weakly-tumorigenic MCF-7 breast cancer cell line which was treated with TGFβ1 to induce EMT." (PMID 23593114, 2013). "KLK6 has been reported to interact with the TGFβ1 signal transduction pathway and influence TGFβ1 expression in breast cancer cells." (PMID 22436421, 2012). "Transforming growth factor β1 (TGFB1) T29C and TGF β receptor type 1 (TGFBR1) 6A/9A polymorphisms have been implicated in the modulation of risk for breast cancer in Caucasian women." (PMID 21829601, 2011). "A pull-down reagent comprised of the Pak1-RBD was used as an affinity probe in immunohistochemistry experiments to demonstrate Rac activation in FFPE fixed mouse mammary tumors driven by Neu and TGFβ1." (PMID 21358804, 2011). "In breast cancer patients, TGFB1 T29C (L10P; rs1800470) and TGFBR1 6A/9A remain the two most extensively studied polymorphisms." (PMID 21829601, 2011). "We have observed that the presence of doxorubicin induced the migration and invasion of murine 4T1 and human MDA-MB-231 breast cancer cells similar to the TGFβ1 treated cells in a Boyden chamber assay." (PMID 20442777, 2010). "We found that treatment with TGFβ1 attenuated growth inhibitory activity of doxorubicin, which indicates that the stem cell phenotype induced by TGFβ appears to enable breast cancer cells to acquire resistance to anti-cancer agents like doxorubicin." (PMID 20442777, 2010). "The transforming growth factor beta (TGFβ) receptor inhibitor, LY2109761, that targets the signaling pathway of another top scoring hit, TGFβ1, was synergistic with paclitaxel when used in combination on select breast cancer cell lines grown in 3D culture." (PMID 20576088, 2010). "There is evidence from the Breast Cancer Association Consortium that CASP8 (caspase 8) and TGFB1 (TGF-β1) variants impart risk, albeit low penetrance, for breast cancer." (PMID 17940599, 2007). "This is in agreement with our data indicating that TGFβ1 is an indicator of bad prognostic for breast cancer patients." (PMID 16404434, 2006). "In breast cancer, a number of studies have been engaged to evaluate the potential prognostic value of TGFβ1." (PMID 16404434, 2006). "To date, quantitative determination of TGFβ1 protein level has been performed exclusively in plasma of breast cancer patients." (PMID 16404434, 2006). "Whereas TGFβ1 seems to be confirmed as a marker of bad prognostic in a number of human tumours such as colorectal and prostatic cancers, the impact of TGFβ1 on the progression of breast cancer remains uncertain." (PMID 16404434, 2006). "To clarify the relevance of TGFβ1 as a prognostic marker in human breast cancer, we quantified TGFβ1 protein level in 193 breast tissue specimens." (PMID 16404434, 2006). "As for carcinomas in other organs, TGFβ1 expression is often increased locally and systemically in advanced breast cancers, particularly at the leading invasive edge of the tumour and in metastasis." (PMID 16404434, 2006). "Similarly, Smad3 knockout in breast cancer models blocks TGFβ1-induced MMP9 expression, inhibiting metastasis." (PMID 40646747, 2025). "In breast cancer, lactate modulates cancer cell invasion via the TGFβ1/Smad3/MMP2/9 signaling axis." (PMID 40646747, 2025). "Therefore, our study provided significant insights into the expression patterns of TGFβ1 and CXCR4 and their involvement with other proteins, for instance VCAN, and WNT whose role is known in causing breast cancer stemness and hence cancer aggressiveness." (PMID 41348904, 2025).
breast cancer (continued). "We have previously shown that tumor stromal expression of TGFβ-1 is associated with TNBC and is a poor prognostic marker of overall survival in breast cancer patients, which is consistent with other studies that linked TGFβ signaling to drug resistance and poor survival rate in TNBC patients." (PMID 38267626, 2024). "We postulate that estrogen receptor-positive breast cancer patients may benefit from high levels of TGFB1 expression due to the repression of estrogen receptor signaling, inhibition of proliferation, and induction of apoptosis in cancer cells." (PMID 39468555, 2024). "The observed proapoptotic and antiestrogenic effects of TGFB1 treatment in MCF7 cells may suggest the prognostic value of TGFB1 expression in breast cancer patients." (PMID 39468555, 2024). "TGFβ1 and TGFβ2 were also more likely to increase OR for breast cancer in LA women." (PMID 38541912, 2024). "Furthermore, increasing serum levels of MIP-1b/CCL4 and TGFβ1 and β2 increased OR for breast cancer at the age ≤ 50 years group." (PMID 38541912, 2024). "The role of TGFβ in providing breast cancer cells with metastatic capabilities – such as inducing epithelial-to-mesenchymal transition and priming cells for extravasation, has been well established for TGFβ1." (PMID 38831405, 2024). "Next, we determined whether DVL2 binds to the promoter regions of genes involved in antigen presentation (HLA-A, HLA-C) and T-cell maintenance (STAT1, STAT6, TGFB1) in HER2-positive breast cancer cells." (PMID 36809986, 2023). "As a next step, invasion assays were performed to study whether TGFβ1 could stimulate lymphatic endothelial cells (SV-LEC) to secrete chemoattractants for breast cancer cells with mesenchymal properties." (PMID 38055067, 2023). "To restrict ourselves to possible somatic, tumor-specific mutations with high confidence, we further selected the variants based on their effect on the transcript and their presence in previous breast cancer studies (see “Methods”), leaving us with 1 variant (COSV54683559, TGFB1 gene)." (PMID 37369746, 2023). "While some of these regulatory mechanisms might also be relevant for TN-C expression in tumors (e.g., TGFβ1 in breast cancer), the transcription factor SOX4 has been shown to induce TN-C in many malignancies." (PMID 35785162, 2022). "Finally, soluble factors/proteins in CM, such as TGFβ1, can be simultaneously targeted to block neovascularization and provide optimal treatment against breast cancer." (PMID 35806196, 2022). "High serum TGFβ1 level predicts better survival in breast cancer." (PMID 34020650, 2021). "EGFR could alter TGF-β function from antitumorigenic to protumorigenic in breast cancer 68, while TGFB1 increased fibrogenic gene expression and myofibroblast differentiation." (PMID 34326696, 2021). "However, overexpression of TGFβ1 significantly increased the invasiveness of calycosin-treated breast cancer cells." (PMID 34096887, 2021). "TGFB1 is a regulatory cytokine that can inhibit and promote breast cancer cell lines and tissue." (PMID 34020650, 2021). "Moreover, BATF promoted breast cancer cell migration and invasiveness by increasing TGFβ1 mRNA and protein levels." (PMID 34096887, 2021). "We have demonstrated that K2 not only upregulates production and secretion of TGF-β from highly invasive breast cancer cells but also is crucial in TGFβ1-induced signaling as phospho-SMAD3 levels were significantly decreased in the K2-deficient MDA-MB-231 and 4T1 cells." (PMID 35936112, 2021). "The multifunctional and contradictory roles of TGFB1 in fibrotic activity in the stroma, and in both promoting and suppressing breast cancer development highlights that more investigation is required to determine the role of TGFB1 in mammographic density and breast cancer risk." (PMID 34771552, 2021). "Moreover, stromal injury in bone marrow can reawaken dormant breast cancer cells via the secretion of inflammatory cytokines IL-6 and IL-8 and activate TGFβ1 signaling." (PMID 34064392, 2021).
breast cancer (continued). "Furthermore, calycosin treatment significantly reduced the levels of CD147, MMP-2, and MMP-9 in TGFβ1-overexpressing breast cancer cells." (PMID 34096887, 2021). "However, overexpression of TGFβ1 significantly increased the migration of calycosin-treated breast cancer cells." (PMID 34096887, 2021). "However, later studies showed a positive correlation of BMP5 down-regulation with lower relapse-free survival in breast cancer patients and can be used as a therapeutic strategy combined with TGFβ1 to reduce cellular proliferation." (PMID 31973134, 2020). "Unlike studies in breast cancer and melanoma models in which horizontal transfer of miRNAs cargo caused fibroblast differentiation, we identify osteosarcoma-EV associated TGFβ1 as the major driver of pulmonary fibroblast activation in vitro." (PMID 32751693, 2020). "We speculated that pS134-GR-regulated gene sets important for TGFβ1 signaling may predict prognosis and disease progression in patients with breast cancer." (PMID 32357907, 2020). "However, a combination of aspirin and metformin reportedly increased the levels of TGFβ1 and tumor-suppressor properties of TGFβ1 in 4T1 mouse breast cancer cells and reduced cell viability and induced cell death in these cells." (PMID 32883003, 2020). "Leptin and TGFβ1 seem to promote metastasis and stemness in breast cancer cells." (PMID 31380268, 2019). "The mRNA levels of CSF2, IL8, and TGFβ1 across the 51 breast cancer cell lines are also shown." (PMID 31293831, 2019). "The secretion of TGFβ1 by CAFs drives EMT in breast cancer cells, resulting in elevated levels of cell-ECM adhesion, breast cancer cell invasion and migration, effects which could be abrogated by inhibiting TGFβ signalling." (PMID 31861782, 2019). "Besides promoting a more cuboidal appearance in a TGFβ1-treated breast cancer epithelial cell line, EVOO-derived crude phenolic extract significantly prevented TGFβ1 from upregulating SMAD4 and SNAIL2, hence allowing the cells to retain E-cadherin expression." (PMID 31315241, 2019). "First, TGFβ1 and IL8 had higher average expression levels in more malignant cell lines; second, MIF and VEGFA had higher average expression levels in more malignant breast cancer tissues, and the high expression levels were associated with poor survival rate." (PMID 31293831, 2019). "In addition, HER2+ breast cancer cells confer trastuzumab resistance by secreting exosomes containing immunosuppressive cytokine TGFb1 and the lymphocyte activation inhibitor PDL1-." (PMID 30940145, 2019). "A 2011 study evaluated breast cancer risk associations with eight SNPs identified through GWAS and two in the candidate genes caspase 8, apoptosis-related cysteine protease (CASP8), and transforming growth factor, beta-1 (TGFβ1) by immunohistochemistry-defined subtypes." (PMID 31379942, 2019). "Moreover, clinical breast cancer samples were also found to highly express TGFB1/2/3 suggesting that these findings are of clinical relevance." (PMID 31533776, 2019). "We found that TGFB1/2/3 are highly expressed in both breast cancer cell lines and tissues." (PMID 31533776, 2019). "In addition, we demonstrated, for the first time, that ADAMTS9 inhibits AKT signaling, through suppressing its upstream activators EGFR and TGFβ1/TβR(I/II) in breast cancer cells." (PMID 29193730, 2018). "Hence, we define TGFβ1 as a regulator of MET expression in breast cancer by upregulating C‐ets‐1 and downregulating miR‐128‐3p expression, which results in cell migration, invasion, and metastasis in a HGF‐dependent manner." (PMID 30004628, 2018). "Furthermore, ADAMTS9 inhibits the AKT pathway through suppressing EGFR and TGFβ1/TβR(I/II) in breast cancer cells." (PMID 29193730, 2018). "Therefore, we quantified levels of TGFβ1 protein in conditioned media harvested from cultured breast cancer and lung cancer brain metastasis cells." (PMID 29844613, 2018).
breast cancer (continued). "It has been reported that TGFβ1 downregulates miR‐128‐3p expression in breast cancer cell lines, which could be confirmed in our model system MCF10A." (PMID 30004628, 2018). "The transforming growth factor beta 1 (TGF-β1) is overexpressed in breast cancer and regulates these processes through the initiation of the TGF-β cellular signaling pathway, which induces the genetic expression and the cellular processes as response to stimuli on the outside of the cell." (PMID 30594253, 2018). "Thus, with both expression and intervention studies in two breast cancer cell lines, we extend the significance of the TGFB1 pathway to being a downstream mediator of leptin signalling for EMT / CSC changes in breast cancer cells." (PMID 28542577, 2017). "Furthermore, the invasive capacity of malignant breast cancer cells is enhanced by TGFβ1 and inactivation of TGFβ signaling inhibited invasiveness in vitro and in vivo for colon carcinoma cell lines." (PMID 28915803, 2017). "In breast cancer, TGFβ1 treatment induces EMT via HOTAIR expression." (PMID 28931862, 2017). "In addition, JAG1, a potent downstream mediator of TGFB1, which promotes osteolysis in breast cancer cells by activating the NOTCH signaling pathway, leads to increased IL6 expression." (PMID 28319320, 2017). "Similarly, platelets isolated from breast cancer patients display a higher degree of pro-angiogenic and metastatic growth factors; for example, TGFβ1, VEGF, and platelet-derived growth factor (PDGF), compared to a control group." (PMID 28737696, 2017). "These trends were particularly contrasting in the plasma profile since all the markers quantified in plasma i.e. NRP-1, VEGF, TGFβ1 and PlGF indicated opposing trends in early onset breast cancer vs older cases, with comparable variability in both healthy controls and breast cancer cases." (PMID 28607365, 2017). "The relationship between TGFB1 and leptin signalling leads to the suggestion that treatment of obese breast cancer patients with drugs that can reduce leptin levels or antagonize TGFB1 signalling may be beneficial in prevention of metastatic disease." (PMID 28542577, 2017). "hsa-mir-106b expression determines the proliferation paradox of TGFB1 in breast cancer cells." (PMID 28684851, 2017). "A few studies have suggested that TGFB1 is critical to both obesity and breast cancer." (PMID 29156709, 2017). "We demonstrated that leptin treatment of breast cancer cells can increase TGFB1 expression." (PMID 28542577, 2017). "To investigate whether the feedback loop actually takes effect in cancer cells, we treated the breast cancer cell line MCF10AT with the TGFβ1 cytokine in a time course of 6–72 h, and then examined the SMAD7 expression." (PMID 27996004, 2016). "Interestingly, we found a dataset that showed that MDA-9 and TGFβ1 were co-expressed in a set of breast cancer patients." (PMID 27863394, 2016). "Using an ex vivo 3-D assay, we confirmed TGFβ1 as a strong candidate for reduced mammary invasion in SPRET/EiJ, which could explain resistance of this strain to mammary cancer risk following LDIR." (PMID 25747469, 2015). "Interestingly, the effect of TGFβ1 expression on the outcome of breast cancer was observed to be limited to tumors with higher T and N stages." (PMID 26040677, 2015). "This family of miRNAs is induced by TGFβ1 and promotes breast cancer metastasis." (PMID 26572553, 2015). "Transforming growth factor beta-1 (TGFβ-1) is a strong inducer of type-3 EMT in mammary cancers." (PMID 25744631, 2015). "The investigations of effects of fucoidan on TGFβ1-promoted carcinogenesis in MDA-MB-231 breast cancer cells have indicated that fucoidan decreased the expression of TGFRs and affected the downstream signaling molecules, which are involved in TGFβ1-mediated EMT." (PMID 25874926, 2015). "On one hand several studies observed that higher TGFβ1 levels in tumors or in the blood of breast cancer patients could predict a better outcome and less distant metastases." (PMID 26040677, 2015).